BCL2 (BCL2 apoptosis regulator)
Diseases named in the same sentence as BCL2 in open-access papers (continued):
Sharing a sentence is not in itself a finding about the gene and the disease.
melanoma (continued). "For instance, it has been shown that Sorafenib down-modulates the levels of Bcl-2 and Bcl-XL, and such down-modulation was shown to be MAPK-independent in A2058 and SKMEL5 melanoma cells but not in A375 cells." (PMID 25188314, 2014). "Using the Broad-Novartis Cancer Cell Line Encyclopedia we did not see a correlation, however, between BCL2 levels pre-treatment and sensitivity to BRAF inhibition as measured by IC50 across 22 BRAF mutant melanoma cell lines." (PMID 24983357, 2014). "It was also reported that aberrant NOTCH1 activation can induce BCL-2 overexpression and increase cell survival, and the noncanonical activation of NOTCH1 by membrane type matrix metalloproteinase sustains melanoma cell growth." (PMID 25149541, 2014). "Finally, analysis of database of melanoma patients showed a significant correlation between the expression levels of HK2 and MCL1 (p = 2.3e-06, rho = 0.216) –but not BCL-2 (p = 1.98e-01, rho = 0.059) or BCL2L1 (p = 4.57e-01, rho = 0.034)." (PMID 41326406, 2025). "We demonstrate here that the lack of efficacy of this combination in melanoma may be due to their dependence on MCL1, rather than BCL2 for survival." (PMID 34451846, 2021). "Moreover, as demonstrated for melanoma cells, IL-1β, COX-2 and CCL2 were upregulated in bcl-2 overexpressing H1299 cells, while IL-8 was not affected and IL-17 was undetectable." (PMID 32269145, 2020). "For example, asiatic acid studied in human melanoma cells (SK-MEL-2) showed an increased level of ROS and hence increased the expression of pro-apoptotic Bax protein, without affecting the expression level of Bcl-2 protein." (PMID 32977472, 2020). "Furthermore, immunoblotting analysis of a panel of melanoma cell lines suggested a correlation between basal mTORC1 activity and the levels of MCL1-but not Bcl-2-in most of those cells, suggesting that MCL1 may play a role in regulating mTORC1 basal activity." (PMID 41326406, 2025).
prostate carcinoma (502 papers, 1996 to 2026). A carcinoma that arises from epithelial cells of the prostate gland. "miR-204-5p acts as a tumor suppressor in laryngeal squamous cell carcinoma (LSCC), targets anti-apoptotic protein BCL2 in prostate cancer (PCa) and serves as an early diagnostic biomarker in endometrial cancer (EC)." (PMID 40395370, 2025). "Abnormalities in the expression levels of Bcl-2 and Bcl-2-associated X protein are consistently associated with increased failure after external beam radiotherapy for prostate carcinoma." (PMID 37241040, 2023). "Vitexin has a cytotoxic effect on breast, ovary, and prostate cancer cells by upregulating BCL2-associated X protein (Bax) and downregulating BCL2 and causing the breakage of the poly[adenosine diphosphate (ADP)-ribose] polymerase (PARP) protein." (PMID 36937314, 2023). "The strong combined effects of ROB and DOC on prostate cancer cells were associated with suppression of NF-κB, downregulation of Bcl-2 and upregulation of Bax." (PMID 34986722, 2022). "Mechanistic study showed that the combined effects of ROB and DOC on prostate cancer cells were associated with inhibition of NF-κB activation, down regulation of Bcl-2 and up regulation of Bax." (PMID 34986722, 2022). "BCL-2 proteins have also been implicated in resistance to radiotherapy in prostate cancer, and an elevated BCL-2/BAX ratio is associated with radioresistance." (PMID 35008216, 2021). "The apoptotic effects of ursolic acid against PC3 cells are mediated by the downregulation of Bcl-2, whereas its antitumor effects in prostate cancer growth in nude mice were associated with the suppression of NF-κB and STAT3 pathways." (PMID 33920405, 2021). "In our study, we showed that Bcl-2, which is associated with the emergence of androgen independence of prostate cancer, is a target of miR-143 using bioinformatics analysis, which is further confirmed by luciferase assay." (PMID 34170852, 2021). "Bcl-2 which is an anti-apoptotic protein, plays a pivotal role in prostate cancer and has been linked with poor prognosis and relapse of the disease." (PMID 32854238, 2020). "We observed that increased expression of Bcl-2 following IORT in prostate cancer cells was associated with an increased risk of a local relapse." (PMID 32341393, 2020). "BCL2, a common target of mir-196b-5p and miR-200b-3p implicated in the apoptosis cascade, is also involved in “colorectal cancer”, “prostate cancer”, and “neurotrophin signaling pathway”." (PMID 32365560, 2020). "Generally, up-regulation of Bcl-2 expression is found in solid tumors including prostate cancer, and it is known to be one of the causes of resistance against radiation therapy." (PMID 32831047, 2020). "N-cadherin was shown to upregulate Bcl2 (B-cell lymphoma 2), which encodes an anti-apoptotic factor in human prostate cancer cells." (PMID 31835801, 2019). "Recent studies recognized Bcl-2 as a biomarker for prognosis of prostate cancer and others showed association of high Bcl-2 expression with higher Gleason scores and lower survival in patients with advanced prostate cancer." (PMID 29357840, 2018). "This study provides evidence that the homozygous BCL2-938 CC genotype is associated with OS and C in prostate cancer patients." (PMID 28396899, 2017). "In the current study, the authors have therefore deliberately decided to analyze only the BCL2 gene variant with the highest prior probability for a positive association with prostate cancer mortality." (PMID 28396899, 2017). "The association between BCL2-938C>A (rs2279115) genotypes and prostate cancer outcome was studied within the prospective PROCAGENE study comprising 702 prostate cancer patients." (PMID 28396899, 2017). "The current study found a strong association of the BCL2-938 CC genotype with reduced survival in prostate cancer patients." (PMID 28396899, 2017).
prostate carcinoma (continued). "The BCL2 c.-938C>A polymorphism is the only BCL2 variant that has been shown to influence BCL2 expression and has been linked to prostate cancer prognosis in a previous study." (PMID 28396899, 2017). "This study provides evidence that the homozygous BCL2-938 CC genotype is strongly associated with reduced OS in prostate cancer patients." (PMID 28396899, 2017). "Results from the Kaplan–Meier analysis, as well as data from a previous study in prostate cancer patients, suggested a recessive effect of the BCL2-938C allele on survival." (PMID 28396899, 2017). "Anvari and coworkers reported an association of high BCL2 expression with higher Gleason scores (GS) and lower biochemical recurrence-free survival in patients with advanced prostate cancer undergoing androgen deprivation therapy (ADT)." (PMID 28396899, 2017). "Aim of the present study was to test a possible association between BCL2-938C>A genotypes and prostate cancer outcome." (PMID 28396899, 2017). "The effects of α-tomatine and curcumin on growth inhibition and apoptosis in prostate cancer cells were associated with inhibition of NF-κB activation and decreased levels of Bcl-2, phospho-Akt and phospho-ERK1/2." (PMID 26630272, 2015). "Compared with benign prostate tissue, higher NF-κB levels are detected in low- and high- grade prostate cancer specimens and are associated with the expression of NF-κB–regulated gene products including Bcl2, cyclinD1, MMP-9, and VEGF." (PMID 26379052, 2015). "Our predictions show that it binds to BCL2-antagonist/killer 1 which causes colorectal cancer, prostate cancer, pancreatic cancer, and tubulin, gamma 1 that causes cortical dysplasia, complex, with other brain malformations." (PMID 26057345, 2015). "BCL2 expression in primary prostate cancer is a marker for poor prognosis, with an increased risk for recurrence." (PMID 24855559, 2014). "For example, its expression is related to decreased survival in chronic lymphocytic leukemia and prostate cancer, whereas increased Bcl-2 expression is associated with favorable outcome in colorectal and breast cancer." (PMID 24088574, 2013). "In this regard, the anti-apoptotic gene Bcl-2 is associated with resistance to radiation, or at least is associated with delay of radiation-induced apoptosis in human prostate cancer cells." (PMID 23351141, 2013). "In cultured PC-3 human prostate cancer cells, sulforaphane-induced apoptosis is associated with up-regulation of Bax, down-regulation of Bcl-2 and activation of caspase-3, -9, and -8." (PMID 23670020, 2013). "Bcl-2 has also been implicated in the development of androgen independent prostate cancer because of its increased expression in the advanced stages of disease." (PMID 24282788, 2013). "Surprisingly, a frequent hypermethylation of two CpG in the Bcl2 promoter was observed in prostate cancer and was associated with a decrease in Bcl2 expression." (PMID 24709797, 2013).
prostate carcinoma (continued). "The over-expression of Bcl-2 is implicated as a cause of hormonal and chemotherapy resistance and has been shown to increase with castration in prostate cancer." (PMID 20178647, 2010). "ADT treatment triggers an overexpression of Bcl-2 which can lead to androgen independence, a condition associated with advanced prostate cancer." (PMID 19589167, 2009). "Others have reported that the mechanism of zinc associated prostate cancer cell death is apoptotic with a shift in Bax/BCL2 ratios and the morphological changes seen in our studies are consistent with apoptotic cell death." (PMID 19534805, 2009). "Expression of Bcl2 has also been associated with poor prognosis in patients with various cancers including prostate cancer." (PMID 15357873, 2004). "Studies in, for example, myeloid leukaemia, carcinoma of prostate and large cell Non Hodgkins lymphoma, have found bcl-2 expression to be associated with a poor response to treatment, and a shorter disease free and overall survival." (PMID 12085183, 2002). "There is evidence that some members of the bcl-2/cd9 family regulate programmed cell death in an evolving manner concerning prostate cancer and an over-expression of bcl-2 is associated with progression and an androgenresistant phenotype." (PMID 11500787, 2001). "Overexpression of anti-apoptotic proteins (e.g., Bcl-2, Bcl-xL, Mcl-1) is a common hallmark across various cancers, often exhibiting distinct patterns of expression in different cancer types such as breast, gastric, lung, and prostate cancers." (PMID 40841912, 2025). "It has been reported that high levels of Bcl-2 are associated with the significant suppression of doxazosin-induced anoikis and cell invasion, which contributes to the survival and proliferation of prostate cancer cells." (PMID 38535120, 2024). "Additionally, a previous study has demonstrated that downregulation of Bcl-2 enhances the chemosensitivity in PTEN-mutated prostate cancer cells." (PMID 38966207, 2024). "In a detailed study using fisetin, the blocking of Akt by exogenous siRNA in prostate cancer cells (LNCaP) caused an elevated Bad and Bax expression, and decreased expression of Bcl-2 and Bcl-xL, which suggested that these effects are mediated in part through Akt." (PMID 31064104, 2019). "Interestingly, the association of increased levels of Bcl-2 and Bcl-XL expression and the progression from localized to disseminated stages using an androgen-independent prostate cancer phenotype has been established previously." (PMID 29357840, 2018). "Third, ectopic Bcl-2 overexpression has been implicated in downregulation of SOCE in both HeLa and LNCaP prostate cancer epithelial cells, which could be attributed to Bcl-2's ability to reduce ER Ca2+ loading." (PMID 30416758, 2018). "Our data also revealed that TA treatment reduced the protein level of Bcl-2, which might be associated with cell cycle arrest and apoptosis in prostate cancer cells, which is consistent with previous reports." (PMID 29518944, 2018). "AgNPs exhibited a strong inhibitory effect on the prostatic cancer PC-3 cells, which might be associated with a decrease of stat 3, bcl-2, and survivin, as well as an increase in caspase-3." (PMID 27316741, 2016). "Several studies have linked overexpression of the antiapoptosis protein bcl-2 with decreased expression of the proapoptotic protein bax, and adverse outcomes in prostate cancer are associated with resistance to cytotoxic chemotherapy in patients with hormone-refractory disease." (PMID 25908947, 2015).
prostate carcinoma (continued). "The recently discovered proteasome inhibitor PS-341 (bortezomib (Velcade®)) has been associated with decreased production of bcl-2, inhibition of nuclear transcription factor κB (NFκB), and prevention of acquired resistance to chemotherapy in prostate cancer experimental systems." (PMID 25908947, 2015). "Depletion of Bcl2 may also contribute significantly to the anti-cancer efficacy of gal, as Bcl2 is known to cause chemo-resistance in prostate cancer." (PMID 26196320, 2015). "AMP showed the more potent activity in inhibiting the proliferation of androgen-sensitive LNCaP and, to less extent, androgen-independent PC-3 human prostate cancer cell lines in vitro, primarily by induction of apoptosis associated with down-regulation of bcl-2." (PMID 22693649, 2012). "Indeed, more than 80% of prostate cancer samples with increased Bcl-2 expression were also found to have a loss of PTEN." (PMID 24212771, 2011). "Resistance to radiation therapy in human prostate cancers has been strongly linked to Bcl-2." (PMID 19589167, 2009). "In particular, Bcl-2 overexpression is associated with prostate carcinoma." (PMID 17637928, 2007). "The higher frequency of bcl-2 immunostaining in tumor samples was observed in association with more advanced Gleason scores and suggests that an increase in the ratio of this anti-apoptotic protein often occurs during progression of prostate cancers." (PMID 11500787, 2001). "Given its crucial role in promoting resistance and progression, Bcl-2 presents a promising therapeutic target in prostate cancer." (PMID 40841912, 2025). "For example, biseugenol B was found to induce apoptosis in PC3 prostate cancer cells by inhibiting NF-κB translocation and altering the Bax/Bcl-2 ratio, leading to cytochrome c release and subsequent caspase activation." (PMID 40542303, 2025). "For instance, O. sanctum ethanolic extract activated caspases 3 and 9 and downregulated BCL-2 in LNCaP prostate cancer cells, leading to DNA fragmentation and cell death." (PMID 40218923, 2025). "The regulation of Bcl-2 expression in prostate cancer is complex and involves mechanisms such as DNA methylation and the influence of lineage plasticity factors like ASCL1 (Achaete-scute homolog 1)." (PMID 40841912, 2025). "Overexpression of Bcl-2 is a critical factor in prostate cancer progression, facilitating tumor growth and increasing tumor cell survival." (PMID 40841912, 2025). "In line with findings from previous reports, LBPs downregulates the Bcl2 gene in human prostate cancer cells." (PMID 39941931, 2025). "Treatment of prostate cancer cells with butein for 48 h resulted in a decrease in Bcl-2 expression, an increase in Bax expression, and an increase in caspase-3 activity." (PMID 40566490, 2025). "These factors are essential, as Cyclin D1 is pivotal for cell cycle regulation, while Bcl-2 plays a crucial role in promoting cell survival, thus highlighting the importance of aberrant AR signaling in the pathology of prostate cancer." (PMID 40008000, 2025). "This study highlights the potential of SSA as a therapeutic agent for prostate cancer by identifying its key molecular targets (BCL2, ESR1, HIF1A, and STAT3) and validating its anti-proliferative and pro-apoptotic effects in PC3 cells." (PMID 39995416, 2025). "Using transcriptomic data from patients with mCRPC in the SU2C/Prostate Cancer Foundation cohort, we observed that Mcl-1 and Bcl-xL had higher expression than Bcl-2, indicating that Mcl-1 and Bcl-xL are potential targets in mCRPC." (PMID 40704654, 2025). "In this context, one study demonstrated that 22Rv1 cells exhibit nearly undetectable BAX protein levels and that blocking Akt, which targets the BCL-2 signaling pathway, sensitizes castration-resistant prostate cancer cells to enzalutamide." (PMID 40126263, 2025).